PROK1 (prokineticin 1)
Diseases named in the same sentence as PROK1 in open-access papers (continued):
Sharing a sentence is not in itself a finding about the gene and the disease.
intrauterine growth restriction (4 papers, 2014 to 2024). "In pregnancy-related diseases, PROK1 is related to preeclampsia 14, recurrent miscarriage 15, intrauterine growth restriction 14, premature birth 16 and other diseases." (PMID 38164347, 2024). "Mechanistically, elevated PROK1 may reduce blood flow and oxygen supply to the placenta by affecting VEGF contraction, which in turn increases the risk of intrauterine growth restriction, fetal distress, neonatal asphyxia, and other adverse pregnancy outcomes." (PMID 39625119, 2024). "In addition, elevated serum PROK1 levels in early pregnancy predict PE and intrauterine growth retardation." (PMID 39625119, 2024). "Thus, inappropriate expression and/or dysfunction of PROK1 may lead to major complications of pregnancy, such as recurrent implantation failure, recurrent pregnancy loss (RPL), ectopic pregnancy (EP), fetal growth restriction (FGR), choriocarcinoma, and pre-eclampsia (PE)." (PMID 38164347, 2024).
preeclampsia (4 papers, 2013 to 2023). Preeclampsia is a hypertensive disorder of pregnancy that is characterized by new-onset hypertension with proteinuria presenting after 20 weeks of gestation, and depending on mild or severe forms may initially present with severe headache, visual disturbances, and hyperreflexia. "The primary objective of this study was to investigate if s-PROK1 predicts pregnancy-induced hypertension, preeclampsia and late miscarriage/preterm delivery." (PMID 37989369, 2023). "The primary aim of this study was to investigate if s-PROK1 predicts pregnancy-induced hypertension, preeclampsia and late miscarriage/preterm delivery in women with PCOS." (PMID 37989369, 2023). "The findings could unveil the possible prophylactic use of VEGFR2 agonists in women with a predilection for preeclampsia and the potential use of PROK1 agonists in the treatment of fetuses with growth restriction." (PMID 23696833, 2013). "Serum prokineticin-1 (s-PROK1) in the second and third trimester of pregnancy is positively correlated to preeclampsia, intrauterine growth restriction (IUGR) and preterm delivery." (PMID 37989369, 2023). "s-PROK1 did not predict pregnancy-induced hypertension (n=15) (OR 0.95, 95% CI 0.32 to 2.74, p=0.92), preeclampsia (n=15) (OR 0.47, 95% CI 0.14 to 1.35, p=0.17) or late miscarriage/preterm delivery (n=20) (OR 0.62, 95% CI 0.24 to 1.56, p=0.32)." (PMID 37989369, 2023). "s-PROK1 was not measured at gestational week 32 and 36 either, as these late timepoints would not hold predictive values for gestational diabetes, early onset preeclampsia or late miscarriage." (PMID 37989369, 2023).
colon cancer (2 papers, 2023 to 2026). "Mice injected with colon cancer cells exhibited a significant increase in median survival time when treated with the anti-PROK1 mAb." (PMID 38275664, 2023).
hyperandrogenism (2 papers, 2023 to 2025). Excessive secretion of androgens from the adrenal glands or gonads. "A possible association between s-PROK1 and hyperandrogenism was also investigated." (PMID 37989369, 2023). "We hypothesised that metformin treatment was associated with lower, and hyperandrogenism with higher s-PROK1 in the second trimester." (PMID 37989369, 2023). "Further studies are needed to determine the exact role of s-PROK1 in pregnancy complications and the involvement of metformin and hyperandrogenism in the regulation of PROK1 in PCOS." (PMID 37989369, 2023). "PCOS women with hyperandrogenism exhibited lower s-PROK1 compared with normo-adrogenic phenotypes." (PMID 37989369, 2023). "Women who used metformin at conception and during pregnancy compared with those who used metformin from inclusion or not at all and those with hyperandrogenism compared with normo-androgenism exhibited lower s-PROK1." (PMID 37989369, 2023). "For specific endometrial pathways, hyperandrogenism only plays a role in the presence of hyperinsulinemia, such as the impaired endometrial lipocalin signaling pathway, and DHT-enhanced up-regulation of prokineticin 1 (PROK1) in human embryonic stromal cells (hESC) only in combination with insulin." (PMID 40410881, 2025). "However, the contribution of PROK1 to the development of pregnancy complications and the effect of metformin and hyperandrogenism on s-PROK1 in PCOS have not been studied previously." (PMID 37989369, 2023). "s-PROK1 was analysed using ELISA at gestational week 19 and related to pregnancy complications, fasting insulin levels, homoeostatic model assessment for insulin resistance (HOMA-IR), testosterone, or androstenedione levels, metformin use, PCOS phenotype and hyperandrogenism." (PMID 37989369, 2023).
Hypertension (2 papers, 2023 to 2024). The presence of chronic increased pressure in the systemic arterial system. "Maternal s-PROK1 in the second trimester did not predict pregnancy-induced hypertension, pre-eclampsia or late miscarriage/preterm delivery in women with PCOS." (PMID 37989369, 2023).
polycystic ovary syndrome (2 papers, 2023 to 2024). A disorder that manifests as multiple cysts on the ovaries. "Researchers compared PROK1 expression in 13 pairs of human polycystic ovary syndrome (PCOS) and normal ovary samples." (PMID 38164347, 2024).
small intestinal cancer (2 papers, 2015 to 2021). "Intensification of PROK1 expression was also observed in advanced-stage gastric and small intestine cancer." (PMID 25788276, 2015).
choriocarcinoma (1 paper, 2024). An aggressive malignant tumor arising from trophoblastic cells. "Prokineticin 1 protein and its two receptors are upregulated in the blood and placenta of choriocarcinoma patients." (PMID 38164347, 2024).
colorectal tumors (1 paper, 2021). "PROK1 expression and the number of lymph vessels were examined in the primary lesion of 391 patients whose colorectal tumors had been resected." (PMID 34262649, 2021). "When PROK1 was expressed in human colorectal tumors, the rate of lymphnode metastasis was significantly higher than that in cases with non-detectable PROK1 expression." (PMID 34262649, 2021).
cyst (1 paper, 2024). A sac-like closed membranous structure that may be empty or contain fluid or amorphous material. "PROK1 was highly expressed in theca interna and stroma of PCOS ovaries, suggesting that the angiogenic function of PROK1 may be related to the cyst formation." (PMID 38164347, 2024).
endometrial adenocarcinoma (1 paper, 2009). "In order to investigate the potential role of PROK1 on the induction of angiogenic factors in endometrial cells, we made use of a human endometrial adenocarcinoma Ishikawa cells, stably expressing PROKR1." (PMID 19348862, 2009).
endometrial polyp (1 paper, 2025). A benign nodular lesion protruding above the surface of the endometrium. "Overall, the figure suggests that while PROKR1 and PROKR2 show the most significant changes, other genes like PROK1, PROK2, and HOXA10 exhibit smaller or non-significant alterations, highlighting the importance of certain prokineticins in the pathology of endometrial polyps." (PMID 39915377, 2025).
glioma (1 paper, 2023). A benign or malignant brain and spinal cord tumor that arises from glial cells (astrocytes, oligodendrocytes, ependymal cells). "Interestingly, glioma patients with higher PROK1 expression had a significantly shorter progression-free survival time further suggesting putative prognostic value of PROK1 in human gliomas." (PMID 36959545, 2023). "We identified 8 plasma proteins which were increased in gliomas vs. meningiomas (GFAP, NEFL, EDDM3B, PROK1, MMP3, CTRL, GP2, SPINT3) and 4 proteins which were decreased in gliomas vs. meningiomas (FABP4, ALDH3A1, IL-12B and OXT)." (PMID 36959545, 2023). "In a recent glioma biomarker discovery study, PROK1 expression in glioma tissue was found to be significantly higher than that in normal tissue (P < 0.05) with higher expression in high grade gliomas compared to low grade ones." (PMID 36959545, 2023).
Miscarriage (1 paper, 2024). A pregnancy that ends at a stage in which the fetus is incapable of surviving on its own, defined as the spontaneous loss of a fetus before the 22th week of pregnancy. "Nevertheless, abnormal expression of PROK1 may lead to impaired endometrial decidualization, trophoblastic dysfunction and placental dysplasia, resulting in pregnancy complications such as recurrent miscarriage, PE and FGR, although the exact mechanisms have not been fully clarified." (PMID 38164347, 2024).
ovarian endometriosis (1 paper, 2023). A non-neoplastic disorder characterized by the growth of endometrial tissue in the ovaries. "Specifically, the expression of KIR2DL4 was remarkably downregulated, while the expressions of PROK1, IGFBP1, RBP4, G2MB, KIR3DL1, and PRF1 were significantly upregulated in ovarian endometriosis." (PMID 37662927, 2023).
cancer (12 papers, 2010 to 2026). A tumor composed of atypical neoplastic, often pleomorphic cells that invade other tissues. "The PI3K/AKT/mTOR pathway can be activated by PROK1, which is associated with almost all human cancers." (PMID 37070074, 2023). "In terms of PROK1 expression in both plasma and primary cancer lesions, the simultaneous PROK1 expression was associated with a poorer prognosis than that in patients without simultaneous PROK1 expression especially among stage III patients." (PMID 34657605, 2021). "In colon cancer, it has been reported that PROK1 expression in primary cancer lesions was associated with tumor recurrence and patient prognosis." (PMID 34657605, 2021). "The association between plasma PROK1 levels and cancer-related survival rate (CRS) was evaluated." (PMID 34657605, 2021). "Furthermore, PROK1 expression in both plasma and primary cancer lesions was more strongly associated with a lower 5-year cancer-related survival rate, especially in stage III disease." (PMID 34657605, 2021). "These PROK1-related malignancies were closely associated with advanced clinical stage, histological grade, and distant metastasis, which may probably through regulating peritumoral angiogenesis or/and strengthened cancer cell invasiveness." (PMID 26828479, 2016). "Our research team has been engaged in extensive studies focusing on PROK1 factor as a target molecule for treating cancer." (PMID 38275664, 2023). "Our findings were similar to those of previous studies that showed PROK-1 induced Akt phosphorylation, upregulated the Bcl-2 family member Mcl-1, and acted as an anti-apoptotic effector in cancer cells." (PMID 37070074, 2023). "We measured preoperative PROK1 plasma levels using ELISA method, while PROK1 expression in primary cancer lesion was evaluated using immunohistochemistry (IHC)." (PMID 34657605, 2021). "Fourth, a little discrepancy of PROK1 expression between plasma and primary cancer lesion was shown in our study." (PMID 34657605, 2021). "PROK1 in the primary cancer lesion positive group included more plasma PROK1-positive patients than in the negative group (P < 0.001)." (PMID 34657605, 2021). "Recent studies showed overexpression of prokineticin-1 not only in several types of cancers such as colorectal, pancreatic, and prostatic carcinoma but also in carcinomas of the testis and in neuroblastomas." (PMID 28386275, 2017). "Relatively less data are available in literature regarding the expression of prokineticin-1 and prokineticin-2 in human cancers." (PMID 28386275, 2017). "Nevertheless, more studies are required to elucidate the role of PROK1 WT and V67I in both human pregnancy and cancers, and the complex interaction between PROK1 and its receptors in various pathophysiologies of human clinical situations." (PMID 26828479, 2016). "G protein-coupled receptors (PROKR1 and PROKR2) are the receptors for PROK1 and are expressed in the endothelial cells and cancer cells themselves." (PMID 25788276, 2015). "Collectively, these observations reveal a dual nature of PROK1 in cancer biology." (PMID 41584032, 2026). "In addition to promoting angiogenesis, PROK1 regulates cell migration and proliferation in normal and cancer cells." (PMID 37070074, 2023). "This provided additional evidence for the proliferative effects of PROK1 in cancer patients." (PMID 37070074, 2023). "The PROK1/PROKR system has potent angiogenic activities in cancer development." (PMID 37070074, 2023). "Interestingly, hCG has been shown to transiently induce PROK1 in Ishikawa cells, a cancer cell line widely used as model for uterine epithelial cells, which was followed by increased LIF expression." (PMID 20422017, 2010). "Patients with high PROK1 expression had significantly higher immunity, stromal, and ESTIMATE (Estimation of stromal and immune cells in malignant tumor tissues using expression data) scores, suggesting that PROK1 may modulate the tumor immune microenvironment to exert a cancer-inhibitory effect." (PMID 41584032, 2026).
cancer (continued). "Additionally, we examined whether simultaneous PROK1 expression in both primary cancer lesions and plasma was correlated with CRS." (PMID 34657605, 2021). "Additionally, PROK1 in plasma may come from both primary cancer lesion and other organs naturally producing PROK1." (PMID 34657605, 2021). "PROK2 along with PROK1 are chemokine-like proteins (attracting leukocytes to an inflammatory site) usually expressed by components of the innate immune system, such as macrophages with specific roles in host defence and angiogenesis during virus-related cancers." (PMID 33121134, 2020). "The PROK1-overexpressing cells in the present study could be a mimicking condition of malignancy, and the increased cell invasion ability suggested the potential role of PROK1 in cancer biology." (PMID 26828479, 2016). "Out of 130 patients, 61 (46.9%) were positive on IHC in primary cancer, and 69 (53.1%) were negative, while 43 (33.1%) had high-value PROK1 in plasma." (PMID 34657605, 2021). "The plasma PROK1-positive patients showed a lower 5-year cancer-related survival rate than patients without it." (PMID 34657605, 2021).
tumor (9 papers, 2015 to 2026). "Further studies are required to examine the cause of the increase in PROK1 expression, including the association between PROK1 and tumor microenvironment." (PMID 34657605, 2021). "Most notably, and in stark contrast to its reported role in other malignancies, our study robustly confirms that PROK1 is expressed at low levels in PCa tissues and functions as a tumor suppressor." (PMID 41584032, 2026). "The xenograft assay was conducted by subcutaneously injecting nude mice with PC3 cells, and it was found that the weight and volume of subcutaneous tumors formed after injection of tumor cells overexpressing PROK1 were smaller than those of the control group." (PMID 41584032, 2026). "This correlation between PROK1's low expression and adverse outcomes in PCa underscores its critical role in tumor development." (PMID 38898043, 2024). "Previous research indicates PROK1's pivotal role in tumorigenesis and progression, potentially impacting tumor malignancy." (PMID 38898043, 2024). "In conclusion, PROK1 knockdown significantly prevented tumor growth and promoted apoptosis of human PC cells in vivo, where the PI3K/AKT/mTOR pathway was probably inhibited." (PMID 37070074, 2023). "We found in this study that the protein level of Bcl-2 decreased and that of Bax and cleaved caspase-3 increased, indicating that PROK1 silencing promoted the apoptotic death of tumor cells transplanted in nude mice." (PMID 37070074, 2023). "This indicated that treatment with sh-PROK1–1 helped to maintain the reduced expression of PROK1 during tumor growth." (PMID 37070074, 2023). "Immunohistochemistry (IHC) revealed that 61 (46.9%) patients were positive for PROK1 expression in the primary tumor, and 30 (25.4%) of them were positive for PROK1 in the plasma." (PMID 34657605, 2021). "The tumor-suppressive role of the key gene PROK1 was experimentally confirmed." (PMID 41584032, 2026). "Furthermore, pathway exploration revealed that PROK1 inhibits tumor growth by mediating apoptosis under copper ion stress." (PMID 41584032, 2026). "Additionally, Prok1 is an angiogenic growth factor with vital roles in regulating the growth of organ blood vessels and tumor blood vessels." (PMID 37025993, 2023). "The size of the tumor in the sh-PROK1–1 group was smaller than that in the shCon group." (PMID 37070074, 2023). "The tumor weight of the sh-PROK1–1 group was lesser than that of the shCon group (P < 0.01)." (PMID 37070074, 2023). "Additionally, PROK1 may activate tumor invasion via matrix metalloproteinases (MMP), especially MMP2, MMP7, and MMP9." (PMID 34657605, 2021). "Upon analyzing the expression of 11 model genes in prostate PRAD, we observed significant differential expression of eight genes (MYADM, MPDZ, LTBP2, DENND4C, PROK1, DDIT4, IGFBP3, and CFD) between normal and tumor tissues." (PMID 38898043, 2024). "For all of the cell lines, tumor formation was significantly suppressed in the presence of both anti-VEGF antibody and anti-PROK1 antibody, compared with when only anti-VEGF or anti-PROK1 was present." (PMID 25788276, 2015). "Our results suggest that angiogenesis and the tumor growth rate are significantly suppressed in the presence of both anti-VEGF and anti-PROK1 antibodies together, compared with in the presence of only one or the other." (PMID 25788276, 2015). "When both anti-PROK1 and anti-VEGF antibodies were simultaneously applied, tumor formation and peritumoral angiogenesis were strongly suppressed, compared with when either anti-PROK1 antibody or anti-VEGF antibody was applied alone." (PMID 25788276, 2015). "PROK1 expression decreased with elevated Gleason scores, tumor grade, and BCR status, suggesting that the progression of PCa may be related to the inhibition of PROK1's oncogenic effect." (PMID 41584032, 2026). "The number of lymph vessels in the primary tumor tissue increased when PROK1 was highly expressed compared to cases with non-detectable PROK1 expression." (PMID 34262649, 2021).
tumor (continued). "This, and the augmentation of tumour-infiltrating macrophages, resulted in positive survival outcomes while the opposite result was obtained with increased PROK1 expression and absence of MCpyV." (PMID 33121134, 2020). "The size of the resulting tumor was 550 mg when no antibodies were added 340 mg in the presence of anti-VEGF antibody, 230 mg in the presence of anti-PROK1 antibody, and 110 mg in the presence of both anti-VEGF and anti-PROK1 antibodies." (PMID 25788276, 2015).
infection (2 papers, 2009 to 2013). The state of being infected such as from the introduction of a foreign agent such as serum, vaccine, antigenic substance or organism. "In this study, we investigated the pro-inflammatory response of fetal membranes to LPS and PROK1 in vivo using a model of infection-induced PTD." (PMID 24051059, 2013). "Infection of Ishikawa PROKR1 cells with an adenoviral construct containing RCAN1-4 reduced the IL-8 mRNA expression in response to PROK1." (PMID 19348862, 2009). "On the other hand, infection of cells with RCAN1 shRNA resulted in an increase in the expression PROK1-induced IL-8 mRNA (p < 0.05) and protein (p < 0.05) compared to cells infected with NT shRNA." (PMID 19348862, 2009). "Thus, PROK1 induction may be part of the infection-induced pro-inflammatory response that contributes to PTD and antagonism of PROK1 could be a therapeutic target in the treatment of PTD." (PMID 24051059, 2013).
neurological disorders (1 paper, 2023). "In conclusion, these data are the first to describe that PROK1 and PROK2 can modulate the permeability of the blood–brain barrier, thus potentially contributing to the regulation of cerebrovascular function and its potential relevance in various neurological disorders." (PMID 37895111, 2023).